GBP3 (guanylate binding protein 3)
Description:
Interferon (IFN)-inducible GTPase that plays important roles in innate immunity against a diverse range of bacterial, viral and protozoan pathogens. Hydrolyzes GTP very efficiently; GDP rather than GMP is the major reaction product (By similarity). Following infection, recruited to the pathogen-containing vacuoles or vacuole-escaped bacteria and acts as a positive regulator of inflammasome assembly by promoting the release of inflammasome ligands from bacteria (By similarity). Acts by promoting lysis of pathogen-containing vacuoles, releasing pathogens into the cytosol (By similarity). Following pathogen release in the cytosol, promotes recruitment of proteins that mediate bacterial cytolysis: this liberates ligands that are detected by inflammasomes, such as lipopolysaccharide (LPS) that activates the non-canonical CASP4/CASP11 inflammasome or double-stranded DNA (dsDNA) that activates the AIM2 inflammasome (By similarity). Exhibits antiviral activity against influenza virus. [Isoform 2]: Shows the most prominent antiviral activity in epithelial cells.
Synonyms: FLJ10961
Tractability: PROTAC: ubiquitination databases record sites on it.
Gene: Protein-coding gene on chromosome 1 (89,006,666 to 89,022,894, reverse strand). Ensembl gene ENSG00000117226.
Subcellular location: Cytoplasm; Cytoplasm, perinuclear region; Golgi apparatus membrane
Pathways (Reactome):
Immune System: CASP4 inflammasome assembly; GBP-mediated host defense; Interferon gamma signaling
Disease: Enterobacterial factors antagonize host defense
Gene Ontology:
Molecular function: identical protein binding; protein binding; protein homodimerization activity; GTP binding; GTPase activity
Biological process: cellular response to interleukin-1; cellular response to tumor necrosis factor; cellular response to lipopolysaccharide; cellular response to type II interferon; cytolysis in another organism; defense response to bacterium; positive regulation of pyroptotic inflammatory response
Cellular component: cytoplasm; cytosol; Golgi membrane; cytoplasmic vesicle; perinuclear region of cytoplasm
Genetic constraint (gnomAD): Loss-of-function variants: 55 observed, 62.99 expected, observed/expected ratio (o/e) 0.87, 90% interval 0.7 to 1.09. The synonymous counts are far from expectation, so gnomAD's model fits this gene poorly and the ratio says little. Missense variants: 605 observed, 713.71 expected, observed/expected ratio (o/e) 0.85, 90% interval 0.79 to 0.91. Synonymous variants: 208 observed, 264.97 expected, observed/expected ratio (o/e) 0.79, 90% interval 0.7 to 0.88.
Homologues: Orthologues: chimpanzee GBP3 (98% identical), macaque GBP3 (93% identical), Drosophila melanogaster atl (19% identical). Paralogues in human: GBP1 (87% identical), GBP2 (74% identical), GBP5 (67% identical), GBP7 (54% identical), GBP4 (53% identical), GBP6 (51% identical), ATL1 (20% identical), ATL2 (20% identical), ATL3 (20% identical), RNF112 (11% identical).
Diseases named in the same sentence as GBP3 in open-access papers:
GBP3 is named in the same sentence as 28 diseases in open-access papers, as found by Europe PMC text mining. Sharing a sentence is not in itself a finding about the gene and the disease. The quoted sentences say what the papers report.
influenza (6 papers, 2020 to 2023). An acute viral infection of the respiratory tract, occurring in isolated cases, in epidemics, or in pandemics; it is caused by serologically different strains of viruses (influenzaviruses) designated A, B, and C, has a 3-day incubation period, and usually lasts for 3 to 10 days. "Proteins that were specifically translated in THP-1 cells following co-culture with 5-OP-RU-stimulated MAIT cells included the Guanylate-binding protein 3 (GBP3), which is known to exhibit antiviral functions during influenza infections." (PMID 36875139, 2023). "Previous studies have shown that GBP1 and GBP3 possess anti-influenza viral activity, killing and transporting antimicrobial peptides to phagolysosomes by oxidation." (PMID 36147849, 2022). "GBP3 also has been reported to contributed to anti-influenza activity via suppressing viral transcription and replication." (PMID 32269280, 2020). "One group of ISGs, as represented by several well-known anti-influenza ISGs (Gbp3, Ifit3, Isg15, and Mx1/2), showed a kinetic pattern of mRNA expression largely resembling that of IFN-γ mRNA, suggesting that they were likely to be directly regulated by IFN-γ in an autocrine manner." (PMID 35296070, 2022). "Interestingly, GBP3ΔC possessed strong anti‐influenza viral activity, while the antiviral function of GBP3 was weak, indicating that the C terminus of GBP3 inhibited the antiviral activity of the LG domain." (PMID 33673837, 2021). "Previous research has demonstrated that a splice variant of hGBP3 (hGBP3-ΔC) with a modified C-terminal α-helical domain effectively resists influenza infection, unlike the full-length GBP3." (PMID 37764102, 2023).
glioma (5 papers, 2019 to 2023). A benign or malignant brain and spinal cord tumor that arises from glial cells (astrocytes, oligodendrocytes, ependymal cells). "A pioneer study pointed out that the GBP3 is highly expressed in glioma, which induces ERK1/2 activation mediated by p62/SQSTM1 and the consequent glioma cell proliferation." (PMID 37189700, 2023). "GBP3 contributes to the glioma cell proliferation via regulating SQSTM1-ERK1/2 pathway." (PMID 33608513, 2021). "Moreover, the silencing of GBP3 and STING in glioma cells diminished the levels of NRF2." (PMID 37189700, 2023).
glioblastoma (3 papers, 2023 to 2025). The most malignant astrocytic tumor (WHO grade IV). "GBP3, though less broadly prognostic, promotes glioblastoma growth when overexpressed, activating pathways such as p62-ERK1/2 to fuel proliferation and resistance, with minimal impact on other cancers’ outcomes." (PMID 40564939, 2025). "GBP3 in glioblastoma upregulates MGMT to repair temozolomide-induced DNA damage, preserving tumor viability and counteracting alkylating agent efficacy, a process facilitated by its diffuse cytoplasmic distribution and GTPase activity." (PMID 40564939, 2025). "Pairing GBP inhibitors with chemotherapy (e.g., paclitaxel, temozolomide) or immune checkpoint blockers (e.g., PD-L1, CTLA-4) could overcome resistance, as seen with GBP5 in breast cancer and GBP3 in glioblastoma—a strategy testable in clinical trials or preclinical models." (PMID 40564939, 2025). "GBP3, while not broadly prognostic, exhibits glioblastoma-specific overexpression, activating p62-ERK1/2 and potentially aiding targeted diagnostics through RNA in situ hybridization, microarray analysis, or proteomic assays." (PMID 40564939, 2025).
atherosclerosis (2 papers, 2018). A disease characterized by the build-up of fatty material and calcium deposition in the arterial wall resulting in partial or complete occlusion of the arterial lumen. "In mice, elevated levels of Gbp3 and Gbp6 were linked with the pathogenesis of atherosclerosis." (PMID 29467757, 2018). "Following a Western-type diet GBP3 and GBP6 expression levels increase during foam cell formation in mice, indirectly suggesting their role in the acceleration of atherosclerosis by hypercholesterolemia." (PMID 30303482, 2018). "Coupled with evidence from our network-based prioritization, this suggests that other members of the GBP family with similar expression patterns to GBP3 and GBP6, including the top-prioritized GBP1, might also play a role in atherosclerosis mediated by hypercholesterolemia." (PMID 30303482, 2018).
colorectal cancer (2 papers, 2022 to 2023). A primary or metastatic malignant neoplasm that affects the colon or rectum. "Highly upregulated genes in 4 days pHe 6.6 cells includes GBP3, a member of the guanylate-binding protein family, which induces caspase-dependent apoptosis in leukemia cells and exerts an anti-tumor role in colorectal cancer." (PMID 37174038, 2023).
leukemia (2 papers, 2021 to 2023). A malignant (clonal) hematologic disorder, involving hematopoietic stem cells and characterized by the presence of primitive or atypical myeloid or lymphoid cells in the bone marrow and the blood. "In this study, we revealed that GBP1–5 are significantly downregulated in AML, ALL, or CLL patients compared with the non-leukemic population, and elevated levels of GBP1, GBP3, GBP4, and GBP6 are associated with prolonged survival time in leukemia and lymphoma patients." (PMID 34294680, 2021). "GBP1, GBP3, GBP4, and GBP6 were beneficial for overall survival, indicating that GBPs are favorable prognosis markers for tested leukemia and lymphoma types." (PMID 34294680, 2021).
breast carcinoma (1 paper, 2013). "Our data suggest that several pathway members, such as Stat1, Ifngr2, Tgtp1, Ifit1, Gbp1 and Gbp3, may be suitable biomarkers for residual disease in breast cancer patients treated with cytotoxic chemotherapy." (PMID 23520493, 2013).
depression (1 paper, 2024). "Notably, a substantial number of upregulated genes associated with depression were identified, such as Ctss, Ifitm3, H2‐K1, Vim, Bst2, Lag3, Cd74, Isg15, Gbp3, and Cxcl10." (PMID 38946585, 2024).
endotoxemia (1 paper, 2018). "Interestingly, we found that GBP2 deficiency fails to significantly inhibit caspase-11-dependent immune responses in endotoxemia; whereas genetic deletion of GBP1, GBP2, GBP3, GBP5 and GBP7 simultaneously blocked endotoxemia-induced caspase-11 activation." (PMID 30587103, 2018).
hearing loss (1 paper, 2022). "Other genes were related to BPD-associated outcomes such as retinopathy of prematurity (ROP, e.g., GBP3, FJX1, HIPK2) and hearing loss (e.g., GJB6, TMEM63B) and mitochondrial energy metabolism (e.g., TOMM7, SLC25A26, SLC25A33, PDK1, PKM, MDH1)." (PMID 35484630, 2022).
osteosarcoma (1 paper, 2023). A usually aggressive malignant bone-forming mesenchymal neoplasm, predominantly affecting adolescents and young adults. "The results showed that 79 DEGs affected the prognosis of osteosarcoma, with PDE4C, CFAP44, CARNS1, GREB1L, ROF207 identified as significant risk factors and GBP1, MSC, GBP3, F13A1, CCL2 as substantial protective factors." (PMID 37796192, 2023).
infection (15 papers, 2013 to 2025). The state of being infected such as from the introduction of a foreign agent such as serum, vaccine, antigenic substance or organism. "To this end, we infected WT, Gbp1–/–, Gbp2–/–, Gbp3–/–, Gbp5–/–, and Aim2–/– mice with F. novicida and monitored their susceptibility to infection." (PMID 35906252, 2022). "We show that mouse GBP1 and GBP3 are specifically required for inflammasome activation during infection with the cytosolic bacterium Francisella novicida." (PMID 35906252, 2022). "Analysis of serum IL-18 showed that Gbp1–/– and Gbp3–/– mice had an impaired ability to produce this inflammasome-dependent cytokine following infection with F. novicida." (PMID 35906252, 2022). "Mice lacking GBP2, GBP5, or multiple GBPs on chromosome 3 (GBP2, GBP2b (GBP1), GBP3, GBP5, GBP7) were significantly more susceptible to infection, revealing a critical role for these proteins in restricting bacterial infection." (PMID 32150572, 2020). "The expression of Gbp3 and Gbp7 increased following infection with L. mexicana." (PMID 40631203, 2025). "Intriguingly, genes such as Ifi204, Irgm1/2, Nos2, Gbp3/7, Usp18, Irf7, Stat1, and Isg15, which were upregulated in response to infection in cells treated with siR_Ctrl, showed decreased upregulation in cells treated with siR_Nostrill following infection." (PMID 39040107, 2024). "Similarly, Gbp3–/– mice (100%) lost more body weight compared with WT mice and succumbed to infection within 7 days, whereas all WT mice survived." (PMID 35906252, 2022). "Our data analysis showed that (GBP2, GBP3, and GBP7 in the type I IFN signaling pathway were significantly upregulated after E30 infection." (PMID 36147849, 2022). "Transcriptomic profiling of MPXV-infected MK2 cells at 7 h post-infection further revealed the upregulation of multiple guanylate-binding protein (GBP) family members, including GBP3, GBP5, GBP6, and GBP7, highlighting a broader antiviral gene program downstream of type I IFN–IRF1 signaling." (PMID 41225161, 2025). "To investigate whether individual GBPs are responsible for IRGB10 recruitment, we overexpressed IRGB10 and one GBP at a time (GBP1, GBP2, GBP3, GBP5 or GBP7) in LA-4 cells followed by infection with F. novicida." (PMID 35906252, 2022). "Importantly, we found that WT, Gbp1–/–, Gbp2–/–, Gbp3–/–, Gbp5–/–, and Aim2–/– BMDMs all released similar levels of IL-1β, IL-18 and LDH in response to infection with F. novicida in the presence of E. coli LPS." (PMID 35906252, 2022). "Similar to infection with S. flexneri, expression of WT, but not catalytically inactive IpaH9.8, drastically reduced levels of GBP1, GBP2, and GBP4, but not GBP3." (PMID 29024643, 2017).
tumor (5 papers, 2020 to 2025). "In addition, low protein expressions of GBP3/7 were expressed in normal tissues, while medium and high protein expressions of them were observed in tumor tissues." (PMID 32269280, 2020). "On the contrary, the expressions of GBP3, GBP4, and GBP5 in tumor tissues were significantly higher than those in normal tissues." (PMID 36246628, 2022). "Second, tumor subsets enriched for microenvironment features, including hypoxia markers (e.g., Slc2a1, Pdk1, Car9), extracellular matrix (ECM) genes (e.g., Matn2, Fn1, Dcn, Col6a1), vasculature (e.g., Cdh5, Pecam1, Vwf), and interferon response genes (e.g., Rsad2, Ifit3, Gbp3, Cxcl10, Cd274)." (PMID 40171265, 2025).
GBP3 also shares sentences with these, for which no sentence is quoted: cancer (5 papers); COVID-19 (2); viral infections (2); Alzheimer disease (1); bacterial infection (1); colon cancer (1); coronary artery calcification (1); Ewing sarcoma (1); gastric adenocarcinoma (1); Hepatitis (1); Hypercholesterolemia (1); lymphoma (1); measles (1); melanoma (1); retinopathy of prematurity (1).